TIGD4 (tigger transposable element derived 4)
Tractability: No criterion of Open Targets' tractability assessment is met for any kind of drug.
Gene: Protein-coding gene on chromosome 4 (152,768,155 to 152,779,732, reverse strand). Ensembl gene ENSG00000169989.
Subcellular location: Nucleus
Subcellular location (Human Protein Atlas): Cytosol; Nucleoplasm
Gene Ontology:
Molecular function: protein binding; DNA binding; nucleic acid binding
Cellular component: nucleus
Genetic constraint (gnomAD): Loss-of-function variants: 21 observed, 26.94 expected, observed/expected ratio (o/e) 0.78, 90% interval 0.55 to 1.12. The upper end of that interval is the gene's LOEUF score, 1.12, which puts it in group 4 of 6, group 1 being the genes least tolerant of losing a copy. Missense variants: 547 observed, 603.25 expected, observed/expected ratio (o/e) 0.91, 90% interval 0.85 to 0.97. Synonymous variants: 187 observed, 215.78 expected, observed/expected ratio (o/e) 0.87, 90% interval 0.77 to 0.98.
Homologues: Orthologues: chimpanzee TIGD4 (99% identical), dog TIGD4 (91% identical), pig TIGD4 (90% identical), rabbit TIGD4 (87% identical), guinea pig TIGD4 (86% identical), mouse Tigd4 (85% identical), rat Tigd4 (85% identical). Paralogues in human: TIGD6 (29% identical), CENPB (28% identical), TIGD3 (24% identical), JRKL (24% identical), TIGD2 (23% identical), JRK (23% identical), TIGD5 (23% identical), TIGD7 (22% identical), TIGD1 (22% identical), POGK (16% identical), POGZ (15% identical).